S100A8 (S100 calcium binding protein A8)
Diseases named in the same sentence as S100A8 in open-access papers (continued):
Sharing a sentence is not in itself a finding about the gene and the disease.
melanoma (continued). "Next, we studied the effect of S100A8 on the metastatic characteristics of melanoma cells." (PMID 32811814, 2020). "In this study, the authors showed that a neutralizing antibody against S100A8/A9 could reduce the formation of melanoma metastases in the lungs of mice." (PMID 33256110, 2020). "MCAM and EMMPRIN are both highly expressed in melanoma and inhibition of the interaction between these receptors and S100A8/A9 could suppress lung metastasis in vivo, thereby representing an interesting target for therapeutic approaches." (PMID 32722137, 2020). "Secretion of soluble factors such as VEGF-A, TNFα, and TGFβ from melanoma and lung cancer models has been previously demonstrated to induce the expression of inflammatory chemoattractants such as S100A8 and S100A9 in the premetastatic lungs, leading to myeloid cell recruitment." (PMID 33233625, 2020). "However, melanoma cells express surface receptors like RAGE or CD147 that bind S100A8/S100A9, thereby migrate into tissues with high expression of S100A8 and S100A9 and initiate metastases." (PMID 31806053, 2019). "Moreover, the percentage of S100A8/A9 positive cells was significantly higher in primary melanoma as well as in metastatic melanoma tissue sections of short-term survivors compared to long-term survivors in two independent TMAs." (PMID 31806053, 2019). "In this study, we investigated gene and protein expression of the TME-derived protein S100A8/A9 in melanoma tissue and analyzed the prognostic and predictive value of serum S100A8/A9 for metastatic melanoma patients and in the setting of immune-checkpoint inhibitor therapy." (PMID 31806053, 2019). "The aim of this study was to investigate whether the tumor microenvironment-derived protein S100A8/A9 qualifies as prognostic marker for melanoma patients, also in the setting of immunotherapy." (PMID 31806053, 2019). "However, most of the melanoma associated antigens, including the MAGE genes, PRAME, S100A8, TRAG3 and MMP19, were more highly expressed in the MM samples than in NHEM." (PMID 18442402, 2008). "Therefore, by producing S100A8/A9 in an injury-like response triggered by melanoma cells, keratinocytes might contribute to initiating the inflammation context, leading to the recruitment of inflammatory cells, including S100A8/A9-producing cells." (PMID 39201498, 2024). "S100A8/A9 expression was remarkably and specifically increased in S100 family members in both the lungs and brain before the onset of metastatic outgrowth in those organs at a relatively early time point (day 7) after the intradermal injection of melanoma cells." (PMID 36142212, 2022). "Thus, TME-associated S100A8/A9, a ligand of the receptor for advanced glycation end products (RAGE), which is upregulated in melanoma, may represent an important biomarker for prognosis." (PMID 36143291, 2022). "Our findings revealed the number of S100A8/A9 expressing cells as a new powerful tissue biomarker, discriminating between non-metastasizing and metastasizing primary melanomas and between short-term and long-term survivors based on primary melanoma tissue and on metastatic tissue." (PMID 31806053, 2019). "Interestingly, we found S100A8/A9 protein expressing cells also in primary melanomas." (PMID 31806053, 2019). "Moreover, existing research has demonstrated that S100A8/A9-neutralizing antibodies exhibit promising therapeutic effects in animal models of myocardial infarction, idiopathic pulmonary fibrosis, ischemia-reperfusion-induced lung injury, melanoma, and atopic dermatitis." (PMID 40270593, 2025). "S100P and S10012 have a diagnostic and prognostic value in many human cancers, while the contribution of S100A8 and S100A9 to melanoma biology is not fully understood." (PMID 40075679, 2025).
melanoma (continued). "B) Our study consisted of two parts: 1) We analyzed liquid biopsies and measured serum S100A8/A9 concentrations at two different time points via ELISA (MRP8/14) in a cohort of 43 stage III and IV melanoma patients treated with ICIs." (PMID 39700646, 2024). "High-plex spatial RNA profiling has been instrumental in revealing cell type-specific biomarker expression in the TME during early melanoma evolution, including prominent expression of S100A8 and S100A9 in melanoma-adjacent keratinocytes." (PMID 38217840, 2024). "We isolated 4T1 TCs and other murine TCs (B16F10 melanoma, MC38 colon carcinoma, ID8 ovarian cancer) transmigrating towards S100A8/A9-included CM within the Boyden chamber in vitro." (PMID 37553342, 2023). "According to our previous study, sCRT promoted the malignant progression of murine melanoma mainly through TLR4- and S100A8/9-mediated MDSC differentiation/generation and recruitment." (PMID 36249426, 2022). "The results showed that HRG quenches the S100A8/A9 binding to the surfaces of both B16-BL6 mouse melanoma cells and A375 human melanoma cells, suggesting that S100A8/A9 loses its binding force to cell surface SSSRs via the formation of a complex with HRG." (PMID 36142212, 2022). "A study conducted to evaluate the differences in the sera between responder and non-responder patients demonstrated an early increase in eosinophil counts as well as a decrease in S100A8/A9 and HMGB1 in responding melanoma patients." (PMID 36012593, 2022). "The myPath Melanoma Test utilizes the expression of 14 signature genes, including PRAME, CXCL9, CXCL10, S100A7, S100A8, and S100A9, and nine reference genes to distinguish BN from CMM." (PMID 35008167, 2021). "Extracellular S100A8/A9 can bind to RAGE and other receptors, thus contributing significantly to the progression of melanoma." (PMID 33256110, 2020). "S100A8/S100A9 binds to the melanoma cell adhesion molecule (MCAM), a highly expressed cell adhesion molecule in melanoma." (PMID 32722137, 2020). "S100A8/A9/RAGE, S100A8/A9-ALCAM, and S100A8/A9/MCAM axes mediate malignant melanoma progression through the activity of nuclear factor kappa beta (NF-κB) and production of reactive oxygen species (ROS)." (PMID 33256110, 2020). "cDNA analysis revealed an upregulation of S100A8 and S100A9 gene expression in melanoma metastases compared to primary melanomas." (PMID 31806053, 2019). "Although we showed that S100A8/A9 is a valuable prognostic marker for stage III and IV melanoma patients and predicts the response to immune-checkpoint inhibition, it is not a specific melanoma marker." (PMID 31806053, 2019). "Serum levels of S100A8/A9 were measured using a specific ELISA in two independent cohorts of 354 stage III and stage IV melanoma patients as well as in two independent cohorts of patients treated with the PD-1 antibody pembrolizumab." (PMID 31806053, 2019). "Consistent with this, we found that the pro-inflammatory cytokines S100A8 and S100A9, as well as the chemokine receptor CXCR4, were highly and significantly upregulated in primary melanomas compared to benign nevi." (PMID 26918341, 2016). "S100A4 levels are lower in metastatic melanoma compared with primary tumors, while S100A7, S100A8, and S100A9 levels appear to be higher in malignant melanoma compared with normal melanocytes." (PMID 19859558, 2010). "Moreover, for S100A8 and S100A9, overexpressed in mestastatic melanoma, in addition to their prognostic role, a predictive role in immunotherapy response has been evidenced." (PMID 38775220, 2024). "With respect to anti-PD-1 treatment, studies on head and neck, gastric, and melanoma have reported high levels of S100A8/A9 in non-responding patients indicating its role in ICI treatment resistance." (PMID 37256148, 2023). "In the present study, we addressed the question of why melanoma cells are not metastasized into the brain at significant levels in mice despite the marked induction of S100A8/A9 in the brain." (PMID 36142212, 2022).
melanoma (continued). "Nonresponding and responding patients with melanoma significantly increased and decreased S100A8/A9 serum levels after the first ipilimumab infusion." (PMID 35003391, 2021). "A highly significant elevation of ID1 was observed in CD33+CD11b+CD14+HLA-DRlow monocytic MDSC in the blood of melanoma patients compared to their HLA-DRhigh counterparts, while expression of ID1 correlated positively with established MDSC markers S100A8/9 and iNOS." (PMID 31953577, 2020). "In vitro, Ab45 could inhibit S100A8/S100A9-stimulated chemotaxis, and in vitro significantly reduced lung metastasis within a melanoma model." (PMID 32722137, 2020). "Interestingly, protein ligands S100A8 and S100A9 and cognate receptor TLR4 were all identified in melanoma EV cargo." (PMID 28424693, 2017). "However, there was a significant difference between the percentages of S100A8/A9 expressing cells in metastasizing primary melanomas compared to non-metastasizing primary melanomas." (PMID 31806053, 2019). "Significantly higher numbers of infiltrating S100A8/A9 positive cells were found in tissue samples of metastasizing primary melanomas compared to non-metastasizing melanomas (P < .0001) and in melanomas of short-term survivors compared to long-term survivors (P < .0001)." (PMID 31806053, 2019). "S100A8/A9 was exclusively expressed by infiltrating immune cells and not by melanoma cells." (PMID 31806053, 2019). "Interestingly, but in accordance with the cDNA data, we did not observe a significant difference between the median percentage of S100A8/A9 expressing cells in nevi and non-metastasizing primary melanomas (TMA1, P = .12)." (PMID 31806053, 2019). "Moreover, our data imply that serum S100A8/A9 could be a valuable prognostic marker for stage III and stage IV melanoma as well as for patients undergoing immune checkpoint inhibition with pembrolizumab." (PMID 31806053, 2019). "However, samples of metastasizing primary melanomas had a significantly higher median percentage of S100A8/A9 expressing cells compared to nevi and non-metastasizing primary melanomas (both P < .0001)." (PMID 31806053, 2019). "Interestingly, S100A8 and S100A9 are not expressed by melanoma cells." (PMID 31806053, 2019).
inflammatory bowel disease (50 papers, 2009 to 2026). A spectrum of small and large bowel inflammatory diseases of unknown etiology. "Nowadays, S100A8/A9 are considered to be risk factors for many inflammatory diseases such as inflammatory bowel disease (IBD)." (PMID 37450409, 2023). "Elevated S100A8 levels have also been found in other inflammatory disorders which are associated with abnormalities of vascular and cardiac function, particularly diastolic dysfunction, such as diabetes, end-stage renal disease, and inflammatory bowel disease." (PMID 26792056, 2016). "Of note, S100A8/A9 (calprotectin) has been considered as a biomarker for inflammatory diseases such as inflammatory bowel disease." (PMID 38042785, 2023). "S100A8/A9 (calprotectin) is already used in the clinic to detect exacerbations of inflammatory bowel disease, and ELISA- or turbidimetric-based methods for measuring calprotectin in plasma or serum are already established in clinical laboratories." (PMID 37773186, 2023). "S100A8/A9 levels in saliva have also been found to be higher in patients with systemic sclerosis and inflammatory bowel disease than in HCs." (PMID 35529863, 2022). "For several inflammatory diseases (e.g., inflammatory bowel disease, various rheumatic diseases, fever syndromes, and forms of vasculitis) S100A8/A9 is recognized to be a useful biomarker." (PMID 35053354, 2022). "Together with S100A8, it forms a heterodimer called calprotectin, which can serve as a biomarker for inflammatory bowel diseases." (PMID 36431795, 2022). "Experimental approaches blocking the S100A8/A9 activity exerted beneficial effects on disease activity in autoimmune and inflammatory bowel disease." (PMID 33238644, 2020). "Furthermore, S100A8/A9 may be a useful biomarker for several inflammatory diseases like inflammatory bowel disease, various rheumatic diseases, fever syndromes, type 2 diabetes, and forms of vasculitis." (PMID 35053354, 2022). "In previous studies, serum S100A8/A9 have been proposed as prognostic biomarkers for disease progression and therapeutic response in inflammatory bowel diseases (IBD)." (PMID 28542507, 2017). "Granulocyte migration through the gut wall into the feces allows determination of fecal S100A8/A9 in patients with inflammatory bowel diseases like Crohn's disease or appendicitis whereas release of S100A8/A9 by endothelial cells could be observed due to leukocyte interaction." (PMID 29180834, 2017). "S100A8/A9 is a useful biomarker for disease activity in the management of inflammatory bowel diseases (IBD) such as Crohn's disease." (PMID 25860480, 2015). "Calprotectin, a dimer of the calcium-binding proteins S100A8 and S100A9, is highly represented in neutrophils, and levels in feces are known to reflect disease activity in other inflammatory bowel diseases." (PMID 31172380, 2019). "S100A8/A9 has shown to be a biomarker of several inflammatory diseases including RA, systemic JIA, inflammatory bowel disease, and AOSD." (PMID 27537874, 2016). "S100A8 and S100A9 are known to have proinflammatory functions and are expressed in many diseases like inflammatory arthritis and inflammatory bowel diseases but also they are expressed in several types of cancer such as lung, colorectal, and liver cancer." (PMID 26273651, 2015). "Often forming heterodimers, S100A8 and S100A9 serve as biomarkers for the diagnosis and therapeutic responses in inflammatory diseases like inflammatory arthritis and inflammatory bowel disease, while blocking their activity resulted in reduced inflammation in mouse models." (PMID 36259488, 2022). "Moreover, S100A8 and S100A9 serve as inflammatory biomarkers in several autoimmune disorders, such as systemic lupus erythematosus and inflammatory bowel disease." (PMID 31023360, 2019). "In the field of gastroenterology, fecal S100A8/A9 is a well-known biomarker for differentiating between inflammatory bowel disease and irritable bowel syndrome (a functional disorder without inflammation)." (PMID 26799323, 2016).
inflammatory bowel disease (continued). "Calcium-binding proteins S100A8 and S100A9, which belong to the S100 protein family and are involved in anti-infective and proinflammatory responses in the form of S100A8/S100A9 heterodimers, are viewed as the alarmins and biomarkers of inflammatory bowel disease." (PMID 35658572, 2022). "Also, serum levels of S100A8/S100A9 showed their utility in monitoring the presence of inflammation in patients with Crohn’s disease or ulcerative colitis, and S100A12 concentrations in the serum of patients with inflammatory bowel disease are correlated with disease activity." (PMID 37627347, 2023). "However, the increased serum S100A8 level may be insufficient in its role as an SLE-specific biomarker, given that it is also observed in many inflammatory diseases such as rheumatoid arthritis and inflammatory bowel disease." (PMID 35529863, 2022).
colitis (43 papers, 2011 to 2025). Inflammation of the colon. "Genes such as C3, Ccl2, Cxcl1, Ifi44, Lcn2, S100a8, and Tnf were strongly induced during colitis, mirroring previously reported inflammation-associated transcriptional responses." (PMID 40806068, 2025). "In summary, we demonstrated for the first time that macrophage RNF128 deficiency promotes colitis progression by suppressing Tollip-mediated autophagic degradation of S100A8." (PMID 39809743, 2025). "We previously revealed that S100a8 and S100a9 are highly activated and play an important role in the process of colitis-associated carcinogenesis, which suggests an attractive therapeutic target for ulcerative colitis and related colon cancer." (PMID 29326691, 2017). "A nutritional supply of S100a8 after birth protected the offspring of MN mothers long-term from severe colitis, underpinning the manifestation of disease susceptibilities early in life and the opportunity of early intervention when causative factors have been identified." (PMID 39366940, 2024). "Maternal malnutrition during nursing increased the risk of fatal colitis in adulthood dramatically compared to mice raised by WN mothers; however, former MN mice could be rescued when neonatally supplemented with S100a8." (PMID 39366940, 2024). "Furthermore, our results demonstrate that the expression of genes related to the pathogenesis and diagnosis of colitis such as Il1β, Lcn2, S100a8 and S100a9 were specifically enhanced in Socs3-deficient neutrophils localized to the colon and spleen." (PMID 37283760, 2023). "To demonstrate the causal relationship between S100a8/9 levels and the exacerbated colitis phenotype in Dok3−/− mice, we treated WT and Dok3−/− mice with the RAGE antagonist FPS-ZM1, which can inhibit the function of S100a8/9 by blocking their binding to the RAGE receptor." (PMID 34743196, 2021). "Peptides targeting S100A8/A9 at the intestinal mucosa have been shown to ameliorate colitis in murine models." (PMID 40963602, 2025). "Nonetheless, further studies are needed to elucidate the precise mechanisms by which CXCL8 and S100A8/A9 drive NET formation in colitis." (PMID 40963602, 2025). "IF staining combined with semi-quantitative statistical analysis showed that the number of S100A8-positive neutrophils in the damaged colon tissue of KO colitis mice increased more significantly." (PMID 41417165, 2025). "Our findings underscore the protective roles of RNF128 in colitis and contribute to the understanding of S100A8 regulation." (PMID 39809743, 2025). "In this study, using single-cell RNA sequencing analysis of mouse colitis tissues combined with immunofluorescence co-staining, we found that Irg1 expression is predominantly upregulated in S100A8-positive neutrophils." (PMID 41417165, 2025). "Taken together, these data indicate that treatment with S100A8-neutralizing antibodies improves colitis in DSS-treated Rnf128−/− mice." (PMID 39809743, 2025). "Overall, our study underscores the anti-inflammatory role of RNF128 in macrophages during the progression of colitis and highlights the potential of targeting the RNF128-Tollip-S100A8 axis to attenuate intestinal inflammation for the treatment of colitis." (PMID 39809743, 2025). "Neutralizing antibodies against S100A8 significantly alleviated the exacerbation of colitis in DSS-treated Rnf128−/− mice." (PMID 39809743, 2025). "An anti-A8 antibody was successfully administered to rats to maintain S100A8 expression in the intestinal tract at low levels and prevent severe colitis." (PMID 39596871, 2024). "When experimental colitis was induced using DSS in transgenic rats with high systemic expression of S100A8 (Tg-S100A8), colitis pathogenesis was alleviated." (PMID 39596871, 2024). "Consistent with previous work, in the DSS mouse model, the expression levels of Cd44, S100a8, S100a9 and Timp1 were greater in the mice with colitis; while the expression level of Ndrg1 was lower in the mice with colitis." (PMID 38778086, 2024).